NOTCH1 (notch receptor 1)
Diseases named in the same sentence as NOTCH1 in open-access papers (continued):
Sharing a sentence is not in itself a finding about the gene and the disease.
breast cancer (continued). "In TNBC cells treated with the microtubule stabilizing agent paclitaxel, surviving breast cancers cells expressed Notch1, Sox2, Oct3/4, c-Myc, c-SRC, c-MET, Nanog, and E-cadherin, and were highly tumorigenic." (PMID 30515368, 2018). "Studies have shown that Notch1 is an important regulator of the EMT and is associated with tumor migration and invasion in breast cancer." (PMID 30333478, 2018). "On the other hand, miR-9, by direct targeting of NOTCH1, can reveal a suppressor-like activity in metastatic breast cancer cells and also epigenetic inactivation of the miR-9 gene has been shown in human BC." (PMID 29868122, 2018). "Increased expression of NOTCH1 and NOTCH3 has been particularly associated with aggressive basal breast cancer." (PMID 30388742, 2018). "In breast cancer, an overexpression of POFUT1 and NOTCH1 was associated with lymph node metastasis and advanced tumor stage." (PMID 30380753, 2018). "Larger studies have shown that expression of Notch1/4 and JAG1 is associated with poor prognosis in breast cancer." (PMID 30515368, 2018). "An ectopic NOTCH1 expression triggers epithelial-mesenchymal transition in human breast cancer inducing tumor growth and metastasis." (PMID 30380753, 2018). "Notch1, which is a key regulator of luminal estrogen receptor (ER+) breast cancers is inversely correlated with the aggressive TNBC/basal-like breast carcinomas and infiltrating Foxp3+ Tregs." (PMID 30061899, 2018). "Quite recently, the ubiquitin ligase Ring Finger protein 8 (RNF8) has been found to regulate Notch1 ICD stability in breast cancer and Notch signaling has been invoked as a control of cellular heterogeneity in TNBC." (PMID 30388742, 2018). "Recurrent gene arrangements involve MAST and Notch family members (Notch1/2), both showing phenotypic effects in breast cancer (e.g., greater proliferation)." (PMID 30515368, 2018). "This is achieved through the “tip and stalk” cell selection procedure and act of the Notch-1, -4, and Dll-4 proteins that are all profoundly involved in the development of breast cancer." (PMID 30111989, 2018). "Breast cancer clinical outcome was accompanied by high expression of Notch-1,-3,-4 pathways, and Notch-2 was identified as a tumor suppressor in many studies." (PMID 30111989, 2018). "A total of 8 gene fusion rearrangements involving either Notch-1 or Notch-2 were discovered in a panel of 89 breast cancer cell lines and tumors." (PMID 29057904, 2017). "Although Notch proteins are known to regulate stemness, and CCR7 to promote tumorigenesis through a number of pathways, to the best of our knowledge this is the first study linking Notch1 to CCR7-dependent regulation of stem-like cells in mammary cancer." (PMID 28137279, 2017). "In contrast to these findings, there have been recent reports that NOTCH1 functions as an oncogene in melanoma, breast cancer, pancreatic cancer, and lymphoma." (PMID 28947978, 2017). "Studies have shown that NOTCH1 activation is beneficial to maintaining the phenotype of cancer stem cells and promote brain metastasis of breast cancer cells." (PMID 29290947, 2017). "In breast cancer cells, miR-30a attenuated the progression of breast cancer by down-regulating the downstream target gene, Notch1." (PMID 29141684, 2017). "MDM2 has been reported to directly interact with NICD1, which leads to the ubiquitination and the transcriptional activation of Notch1 signaling pathway in breast cancer cells." (PMID 28871126, 2017). "Down regulation of Notch1 signaling pathway can sensitize some anticancer drug (s) in trastuzumab-resistant breast cancer cells." (PMID 28030818, 2017). "By contrast, loss-of-function NOTCH1 mutations are relatively common in HNSCC, lung SCC, and breast cancer." (PMID 28938622, 2017). "High Notch1 expression has correlation with progression and poor prognosis of various tumors, including breast cancer 11, ovarian cancer 12, nonsmall cell lung cancer 13 and colorectal cancer." (PMID 28568708, 2017).
breast cancer (continued). "Herein, we performed real-time PCR to relatively quantify the changes in NOTCH1 expression at mRNA level in breast cancer clinical samples." (PMID 28330128, 2016). "In breast cancer cells, Pim-mediated phosphorylation of Notch1 balances cell metabolism, while its inhibition enforces glycolytic metabolism via defects in mitochondrial function, as previously shown for Notch inhibition." (PMID 27281612, 2016). "Taken together, these data suggest that Pim1 counteracts the effects of Notch1 in regulation of breast cancer cell metabolism." (PMID 27281612, 2016). "Molecules involved in these pathways have been shown to activate the PI3K-AKT axis and NFκB, as demonstrated by the use of a γ-secretase (GSI), and Notch-1 inhibitors in pancreatic, colorectal and breast cancers." (PMID 27233074, 2016). "Recent studies showed that Notch1 activation stimulates the migration of breast cancer cells and Notch1 knockdown suppresses proliferation, migration and metastasis." (PMID 27806347, 2016). "While the compound attenuated the activation of Notch-1 in colon cancer and human breast cancer cells, it activates the cleavage of Notch-2 and Notch-4 in human breast cancer (MDA-MB-231) cells." (PMID 26959007, 2016). "We also found that the expression of Notch1 and Beclin1 protein in tissues of patients with breast cancer were negatively correlated." (PMID 27806347, 2016). "NOTCH1 mutations are relatively common in head and neck squamous cell carcinoma (HNSCC), lung SCC and breast cancer, with 5 % to 15 % of tumors harboring protein-coding changes." (PMID 26759717, 2016). "The expression of Notch1 and p62 is inversely correlated with Beclin1 expression in human breast cancer patients." (PMID 27806347, 2016). "Recently, Notch-1 was reported to take part in the regulation of malignant behaviors of breast cancer stem-like cells." (PMID 27801803, 2016). "Another possible mechanism to explain the increased expression of several metabolic genes is that PI3K/Akt signalling is stimulated following Notch activation, as was observed after hyperactivation of Notch1 in breast cancer cells." (PMID 26887408, 2016). "The expression of NOTCH1 in IDC was significantly higher than that of the patients with other types of breast cancer (p value <0.001)." (PMID 28330128, 2016). "Kaplan-Meier survival analysis showed that inverse Notch1/NUMB expression is a strong predictor of DDFS in breast cancer." (PMID 27506933, 2016). "The finds from the present study indicated that upregulation and downregulation of Notch1-IC and Beclin1 expression, respectively, were inversely correlated in patients with breast cancer." (PMID 27806347, 2016). "Leptin significantly elevated the expression levels of Notch1-4, Notch target genes, Hey2 and increased survival in breast cancer cells; in addition, leptin is an inducer of Notch signaling through regulating Notch1-4 expression and/or activation." (PMID 27185268, 2016). "Notch2 has been described as a tumor suppressor in breast cancer cell lines, while Notch1, 3, and 4 are uniformly oncogenic in the breast." (PMID 27148486, 2016). "Inhibition of Notch1 signaling prevents the transformation of breast cancer cells, tumor progression, and metastasis." (PMID 27806347, 2016). "This is different from the observation from breast cancer cells that NOTCH1 inhibition reduced tumour cell growth." (PMID 27456471, 2016). "Our results enable us to pinpoint one novel mechanism by which CCN6 regulates breast cancer cell plasticity implicating a new Slug/Notch1 signaling axis." (PMID 26933820, 2016). "The relevance of these data to human breast cancer is highlighted by the finding that CCN6 protein levels are inversely correlated with Notch1 intracellular activated form (NICD1) in 69.5% of invasive breast carcinomas." (PMID 26933820, 2016). "We respectively evaluated the expression of NUMB and Notch1 in different breast cancer subtypes, ER status and tumor grade." (PMID 27506933, 2016).
breast cancer (continued). "Our research suggests that autophagy functions as a tumor suppressor by suppressing Notch1 signaling in breast cancer, however, additional studies are required to explore the effect of autophagy on other oncogenic pathways in different cancers." (PMID 27806347, 2016). "Aberrant activation of Notch1 signaling produces Notch1-IC in various cancers, including breast cancer." (PMID 27806347, 2016). "For instance, while studies demonstrated that the truncated form of Notch4 has a causative role in the development of mammary tumors in animal models, others reported a possible oncogenic role of Notch1 overexpression in human breast cancer tissues." (PMID 27929540, 2016). "Breast cancer tissues have increased Notch1-IC levels and show decreased levels of phosphorylated Notch1-IC T2512, HIPK2, and Fbw7." (PMID 27689990, 2016). "In this role, Notch4 appears to be particularly important, as knockdown of Notch4 has a much more significant effect on breast cancer stem cell numbers than Notch1 knockdown." (PMID 26880941, 2016). "Phosphorylation-dependent stimulation of Notch1 signaling promotes migration of prostate cancer cells, balances glucose metabolism in breast cancer cells, and supports in vivo growth of both types of cancer cells on chick embryo chorioallantoic membranes." (PMID 27281612, 2016). "Similar drug resistance to Adriamycin, Cisplatin, Etoposide, and Taxol were reported in breast cancer cells and lymphoblastic leukemia cells, both due to intracellular Notch1 signaling." (PMID 26716652, 2016). "Some studies suggested that Notch1 overexpression foreboded a poor prognosis in breast cancer, but other researchers reported different results." (PMID 26121683, 2015). "The Notch mutations were distributed along the length of the four Notch receptor genes, a distribution also observed for NOTCH1 in a smaller breast cancer data set." (PMID 25907971, 2015). "First, MRP1 was shown to be a direct transcriptional target of Notch1 in the multi-drug resistant breast cancer cell line, MCF7-VP." (PMID 26362310, 2015). "Our findings indicate that Notch1 signaling is a promising therapeutic target for preventing breast cancer progression." (PMID 25645291, 2015). "In the current study, we found that Notch1 knockdown in breast cancer cells suppressed the EMT process, tumor growth, migration, and invasion using in vitro and in vivo models." (PMID 25645291, 2015). "Various studies have evaluated the significance of Notch1 expression in breast cancer, but the results have ever been disputed." (PMID 26121683, 2015). "γ-secretase mediated downregulation of Notch signaling followed by reduction in Notch1 downstream products like Hes1 and cyclin D1 by 6-shogaol thus explain its efficacy in breast cancer spheroid cells." (PMID 26355461, 2015). "Recently, several studies have revealed that overexpression of Notch1 and/or Jagged1 indicates a poor prognosis for breast cancer patients." (PMID 25645291, 2015). "For example, in breast cancer, ectopic miR34a expression reduced cancer stem cell properties and increased sensitivity to doxorubicin treatment by directly targeting NOTCH1." (PMID 25980495, 2015). "In this study, our data also showed that NF-κB p65 expression was dramatically downregulated by Notch1 knockdown in breast cancer cells." (PMID 25645291, 2015). "Our meta-analysis demonstrated that Notch1 expression in breast cancer tissues was significantly higher than that in normal breast tissues (pooled OR = 7.21, 95%CI: 4.7–11.07, Cochran Q’s test p = 0.128 and I2 = 37.7%)." (PMID 26121683, 2015). "Domain-associated mutational biases have been reported in several studies focusing on single well-known cancer genes such as the PI3KCA gene in colon and breast cancer, and the NOTCH1 gene in leukemia, breast and ovarian cancer." (PMID 25794154, 2015).
breast cancer (continued). "The first evidence that Notch receptors are breast oncogenes was provided in mouse studies in which active forms of Notch1 or Notch4 formed spontaneous murine mammary tumors in vivo." (PMID 25645291, 2015). "A number of studies have examined the correlation between Notch1 expression and clinical outcome in patients with breast cancer." (PMID 26121683, 2015). "Earlier data from our laboratory have demonstrated the effectiveness of MAbs against the ligand-binding domain of Notch1 in therapeutic targeting of breast cancer stem-like cells." (PMID 26046801, 2015). "Our results highlight the potential use of Notch1 signaling or Slug inhibitors to prevent breast cancer progression." (PMID 25645291, 2015). "In turn, Notch1, which directly regulates c-myc is co-operating with Wnt in enhancing tumorigenesis enriches mammospheres induced in breast cancer by irradiation." (PMID 25821840, 2015). "The effect of Slug silencing or upregulation on the EMT and invasion of breast cancer cells was analyzed, and the effect of Notch1 signaling on Slug expression was determined by the luciferase reporter assay." (PMID 25645291, 2015). "The cross-talk between Notch1 and ER in breast cancer leads to the decreased expression of Notch1 in ER-positive cells." (PMID 26121683, 2015). "With Notch1 over-expression, a poor clinical outcome of breast cancer is correlated, again promoting angiogenesis and thus tumour progression." (PMID 25780927, 2015). "MRP1 and Notch1 were investigated in 29 patients treated with neoadjuvant chemotherapy (NAC) for breast cancer, using immunohistochemistry on matched biopsy (pre-NAC) and surgical samples (post-NAC)." (PMID 26362310, 2015). "Given the uncertainty of causality and inconsistencies among studies, a meta-analysis was performed to unearth the role of Notch1 in the clinicopathological features as well as prognosis of breast cancer." (PMID 26121683, 2015). "We next investigated the expression of a2V and Notch1 in human breast tumor sections of receptor defined breast cancer subtypes." (PMID 26418877, 2015). "Ectopic expression of Notch1 in luminal breast cancer cell MCF-7 and immortalized breast luminal epithelial cell MCF10A induced EMT and acquired CSC phenotypes." (PMID 26121683, 2015). "Considering the cross-talk between Notch with multiple pathways, we surmise that the influence of Notch1 on MFS was reduced in patients with advanced stage breast cancer, most likely due to the redundancy and complexity of diverse signaling pathways." (PMID 26121683, 2015). "Meanwhile, breast cancer cell migration and invasion abilities were inhibited by Notch1 interference." (PMID 25645291, 2015). "Higher Notch1 activity was observed in the basal subtype of breast cancer (OR=2.53; 95% CI, 1.18-5.43)." (PMID 26121683, 2015). "During the development of breast cancer, increased expression of Notch1 was found and correlated with progression from hyperplasia to malignancy." (PMID 26121683, 2015). "Since high EZH2 expression has also been reported in breast cancer, we next turned to a mouse model eliciting mammary tumors upon mammary-specific expression of the activated form of Notch1 (N1ICD)." (PMID 26637281, 2015). "Our data showed that the expression of the Notch signaling downstream genes Hes1 and Hey1 decreased in breast cancer cells with Notch1 inhibition." (PMID 25645291, 2015). "Previous reports have identified that Notch ligand Jagged1 and Notch receptor Notch1 are upregulated in breast cancer." (PMID 26418877, 2015). "The induction of Notch1 by visfatin was suppressed by inhibition of the NF-κB signaling pathway, indicating a role for NF-κB p65 as a positive regulator of Notch1 induction by visfatin in breast cancer cells." (PMID 24970818, 2014). "A significant association between the increased expression of Notch1 and HER2 in breast cancer suggested that Notch signaling pathway should be a therapeutic target, especially for HER2-positive breast cancers with poor prognosis." (PMID 23990015, 2014).
breast cancer (continued). "As expected, our results showed the high level of N1IC expression (75.0%, 112/150) in breast tumor specimens was consistent with our previous findings of up-regulated Notch1 in breast cancer tissue." (PMID 25420528, 2014). "Knockdown of Notch1 or Notch4 inhibited self-renewal and tumorsphere forming ability of breast cancer cells, supporting their roles for the maintenance of cancer stem cells." (PMID 25229616, 2014). "In this study, we show that Notch1 is a downstream target gene of visfatin signaling and describe the role of the visfatin-Notch1 axis in breast cancer cells." (PMID 24970818, 2014). "Our recent observation suggests that Notch1 is involved in the induction of EMT in a novel breast cancer mouse model." (PMID 25287362, 2014). "The Notch1 signaling pathway plays a role in the regulation of mammary tumor stem cell self-renewal and survival." (PMID 24970818, 2014). "In summary, we have identified a pathway that connects visfatin signaling to Notch1 upregulation through NF-κB and shown that downregulation of the visfatin-NF-κB-Notch1 axis inhibits the survival and proliferation of breast cancer cells." (PMID 24970818, 2014). "The expression of p65 and Notch1 in human breast cancer tissues was assessed by immunohistochemistrical analysis." (PMID 24970818, 2014). "The mechanism of SIRT1 and Notch1 signaling in breast cancer progression needs to be further studied in order to harness the potential of SIRT1and N1IC expression in the clinical setting." (PMID 25420528, 2014). "In vivo knockdown experiments of Notch 1 and Notch 4 in tumour-bearing mice showed that the tumour size decreased and there was a reduction of breast cancer recurrence in these mice." (PMID 24599057, 2014). "When primary breast cancer samples are examined, accumulation of activated Notch1 and Notch3 is frequently observed in tumor cells." (PMID 25309874, 2014). "Blockade of NF-κB signaling suppressed the effects of visfatin on Notch1 upregulation and breast cancer cell proliferation." (PMID 24970818, 2014). "A correlation has been made between poor breast cancer prognosis and an increase in the expression of both Notch-1 and survivin in ER-breast cancer and has been described as the Notch-Survivin signaling axis." (PMID 25566499, 2014). "Our data from KM Plotter also demonstrated that higher expression of NOTCH1 results in poor recurrence-free survival in breast cancer but better overall survival in lung cancer." (PMID 25149541, 2014). "In line with our results, the metastasis-prompting function of NOTCH1 has been reported in breast cancer, prostate cancer, esophageal cancer, and melanoma." (PMID 25149074, 2014). "Our previous study suggests Notch1 is involved in the induction of EMT in a novel breast cancer mouse model containing human breast and human bone." (PMID 25287362, 2014). "Notch receptors have been shown to be important for the formation of spontaneous mammary tumors in vivo after overexpression of constitutive, active forms of Notch1 or Notch4." (PMID 24919951, 2014). "It was previously reported that Ki67 is found in 90% of TNBC and its expression correlates to Notch4, which is induced by Notch1 in breast cancer samples." (PMID 24716804, 2014). "It has been reported that Notch signaling pathway is involved in EMT induction and Notch1 is a prognosis marker for breast cancer." (PMID 25287362, 2014). "Here, we provide evidence for the regulation of Notch1 gene expression by visfatin and describe the role of the visfatin-Notch1 axis in breast cancer cells." (PMID 24970818, 2014). "Although most studies have been utilized Notch1 as the readout of Notch signaling, the four Notch receptors, Notch1, Notch2, Notch3 and Notch4, are thought to have different functions in breast cancer." (PMID 25229616, 2014). "Further examination demonstrated that up-regulation of S100A16 promoted EMT via Notch1 pathway in breast cancer cell line MCF-7." (PMID 25287362, 2014).